PRMT5 (protein arginine methyltransferase 5)
Diseases named in the same sentence as PRMT5 in open-access papers (continued):
Sharing a sentence is not in itself a finding about the gene and the disease.
tumor (continued). "Additionally, we have reported that PR5-LL-CM01, a promising inhibitor of PRMT5, has anti-tumor activity in vitro and in vivo in PDAC and CRC27." (PMID 36720900, 2023). "Additionally, in vivo studies verified that MRTX1719 demonstrates potent and enduring inhibition of PRMT5 in a MTAP-deleted tumor xenograft model, reducing its SDMA activity." (PMID 38136401, 2023). "Additionally, preliminary insights unveiled the tumor-suppressive role of PRMT5 in ccRCC, and the signal of PRMT5low significantly predicted aggressive prognosis and the high abundance of PD1+ CD8+ cells in ccRCC." (PMID 37781030, 2023). "Notably, in ATM-deficient MCL lines, PRMT5 inhibition by GSK3326595 resulted in more accumulated unrepaired DNA damage and attenuated MCL-PDX tumor growth." (PMID 37626420, 2023). "While exogenous KLF5 rescued the expression level in PRMT5‐deficient cells, the absence of PRMT5‐dependent KLF5 limited its ability to promote tumour growth." (PMID 37461162, 2023). "PRMT5 can regulate proliferation, differentiation, invasion, and migration of tumor cells." (PMID 36720900, 2023). "We next conducted an investigation to determine whether the administration of GSK595 or silencing PRMT5 could inhibit tumour growth in vivo." (PMID 37461162, 2023). "However, when compared with the SAM non-competitive PRMT5 inhibitor EPZ015666, PRT382 demonstrated superior in vitro anti-tumor activity and improved survival in the Eμ-PRMT5/TCL1 mouse model of CLL/RT in vivo." (PMID 36609611, 2023). "Based on our results, we know that the enzymatic activity of PRMT5 is required for its presence in the nucleus of tumor cells, suggesting that the methylation of key substrates is required for the regulation of its shuttling between the cytoplasm and the nucleus." (PMID 37458145, 2023). "We analyzed GR/PRMT5 interactions in TNBC PDX models including models engrafted from treatment-naïve patients (primary tumor) and TNBC tumors established from residual tumors after neoadjuvant chemotherapy administered in association with GCs (residual tumors)." (PMID 37536978, 2023). "Xenograft models of ACC-I were responsive to PRMT5 inhibition with a block of tumour growth; AL101 determined tumour regression in NOTCH activated ACC-I models and further synergic activity was observed when used in combination with BCL2 inhibitor or palbociclib." (PMID 37795454, 2023). "The function of PRMT5 in malignancy is due to the context with substrate and tumor types." (PMID 36878903, 2023). "We found that in subcutaneous xenografted mice, PRMT5 knockdown in BC cells or regular FKA injection could shrink tumor size compared with that in the untreated group." (PMID 36199122, 2022). "In general, PRMT5 promotes tumor growth and metastasis of GC cells by silencing IRX1.Targeting PRMT5 in GC may inhibit the malignant characteristics of GC and have new therapeutic potential." (PMID 35444235, 2022). "Furthermore, the levels of CUL4A, PRMT5, nuclear p65, total p65, and IκBα in the tumor were assessed by western blotting." (PMID 35333690, 2022). "Subcutaneous tumor model in nude mice showed that PRMT5 inhibitor tadalafil could enhance the antitumor efficacy of 5-FU." (PMID 36474242, 2022). "The inhibition of PRMT5 and anti-tumor activity was observed after multiple doses of PRT811." (PMID 36572880, 2022). "Furthermore, PRMT5/AKT signaling controls the expression of essential EMT transcription factors controlling tumor cell migration and invasion." (PMID 35803962, 2022). "Therefore, these new PRMT5 inhibitors have the potential to become novel molecular targeted drugs that clinically enhance the patients’ tumor cell chemosensitivity, but further study is still needed." (PMID 35563196, 2022). "At this point, it remains unknown whether PRMT5 plays a role in angiogenesis, which is critically involved in tumor growth, metastasis, and development of peripheral vascular diseases." (PMID 35531958, 2022).
tumor (continued). "Altered splicing and retention of un-spliced introns, which may contain Alu or LINE-1 element sequences, can trigger a viral mimicry response, presenting another mechanism by which PRMT5 may regulate tumor fitness and immunogenicity." (PMID 35602594, 2022). "PRMT5 is known to repress the transcription of critical tumor suppressors by inducing histone H4R3 or H3R8 symmetric di-methylation at the promoter regions of targets (H4R3me2s or H3R8me2s), an event proposed as repressive histone modifications in transcriptional control." (PMID 35624451, 2022). "PRMT5 is the major type II arginine methyltransferase, active in a variety of cellular activities, that achieve tumor-promoting effects through methylation-mediated transcription repression, including inhibition of normal expression of the tumor surface antigen proteins in different tumor types." (PMID 36713412, 2022). "Since PRMT5 acts as the master regulator of sDMA and governs multi‐processes depending on the substrates it methylates, the influence of PRMT5 in tumor progression might be dissimilar in different spatiotemporal situations." (PMID 35766227, 2022). "Increasingly evidence suggests that regulation of abnormal angiogenesis by PRMT5 may contribute significantly to tumor growth and metastasis." (PMID 35531958, 2022). "MAPK pathway activation was increased in PRMT5 knockout tumor cells." (PMID 35493527, 2022). "In conclusion, given the selective role of PRMT5 in the tumor microenvironment, more attention should be paid to the mechanism of side effects in immune cells, and combined immunotherapy may maximize the efficacy." (PMID 36713412, 2022). "In light of our result, targeting Prmt5 might also reduce tumor growth indirectly by inhibiting tumor angiogenesis." (PMID 34153034, 2021). "We show that combination PRMT5/PD-L1 inhibition may achieve a better antitumor effect: targeting PRMT5 to directly inhibit tumor cell survival and targeting PD-L1 to overcome the side effects of targeting PRMT5 and enhance immune function." (PMID 35111150, 2021). "Taken together, these data revealed that downregulation of PRMT5 was conducive to tumor inhibition." (PMID 34522232, 2021). "It was reported PRMT5 had an effect on tumor growth 30, we wondered whether tumor cell proliferation changed the tumor size." (PMID 34522232, 2021). "Overall, PRMT5 may act as a tumor-inducing agent in ESCC by modulating LKB1/AMPK/mTOR pathway signaling." (PMID 34124017, 2021). "In tumor cells, PRMT5 regulates the expression of STAT1 and PD-L1." (PMID 34522232, 2021). "PRMT5 was overexpressed in tumor tissue analysis of 179 patients with GC." (PMID 33440687, 2021). "In addition to these tumour suppressor genes, PRMT5 also reduces transcription of RB family tumour suppressor genes including RB1, RBL1 and RBL2 in transformed B‐cell lymphocytic leukaemia cell lines." (PMID 33462997, 2021). "Studies have largely focused on PRMT5 regulating intrinsic changes in tumors; however, the effects of PRMT5 on the tumor microenvironment and particularly immune cells are largely unknown." (PMID 35111150, 2021). "We will further make deeper and more detailed studies about regulation mechanism of PRMT5 on ESCC in the future work, including the inhibition LKB1/AMPK/mTOR pathway and whether PRMT5-siRNA has anti-tumor growth." (PMID 34124017, 2021). "In brief, we unravel a new mechanism about how PRMT5 promotes tumor growth." (PMID 34522232, 2021). "Moreover, PRMT5 suppressed cell pyroptosis pathways in vitro, and enhanced tumor progression in vivo." (PMID 34531375, 2021). "Few reports have been published about how PRMT5 affects immune cells in the tumor microenvironment." (PMID 34522232, 2021). "However, previous studies showed that the anti-tumor effect of AMI-1 is rather mediated through PRMT5." (PMID 34200178, 2021). "Thirdly, PRMT5 is involved in tumor angiogenesis, cell invasion and metastasis." (PMID 34513846, 2021).
tumor (continued). "Biologically, with PRMT5 having multiple control points within and across differing signalling pathways, this agent may be less likely to induce tumour adaptation and resistance, as seen in many targeted therapies." (PMID 34680285, 2021). "Inhibition of PRMT5 in preclinical models leads to reduced tumour growth." (PMID 34680285, 2021). "PRMT5 has become an essential epigenetic regulator for cell proliferation and tumor development." (PMID 34513846, 2021). "Therefore, we tested the effect of PRMT5 knockdown on tumor cell proliferation with CCK8 assay and EdU staining." (PMID 34522232, 2021). "PRMT5 may act as a tumor inducer in esophageal squamous cell carcinoma by regulating the LKB1/AMPK/mTOR signaling pathway." (PMID 34513846, 2021). "GSK3203591 and GSK3368715 have been reported to synergistically inhibit tumor growth in vivo, possibly through a tumor-specific accumulation of 2-methylthioadenosine, an endogenous inhibitor of PRMT5, which correlates with sensitivity to GSK3368715 in cell lines." (PMID 35475236, 2021). "Although PRMT5 inhibition appears to reduce activation and recruitment of the immune system in the periphery compartment, PRMT5 inhibition has an immune promoting effect in the tumour microenvironment." (PMID 34680285, 2021). "Tumor volume and weight were decreased in the PRMT5-depleted group, whereas Wnt4 overexpression could reverse PRMT5-silencing tumor shrinkage." (PMID 33060569, 2020). "Significantly, PRMT5 inhibition in established tumors could disable mechanisms protecting tumor cells from DNA damaging stress brought on by radiotherapy and chemotherapy." (PMID 32743345, 2020). "Direct interaction of PRMT5 with the MEN1 tumor suppressor in pancreatic islet tumors reportedly increases repressive sDMAs on H4 (H4R3me2s) and suppresses Gas1, PTCH1 and c-myc expression, thereby limiting oncogenic SHH (sonic hedgehog) signaling in these tumors." (PMID 32743345, 2020). "Notably, combination treatment of CD26Her2 mouse tumors with targeted therapy (anti-erbB2/neu antibody) plus a PRMT5 inhibitor (DS-437) enhanced anti-tumor effects through Treg suppression and augmented anti-tumor immunity." (PMID 32743345, 2020). "Because NHEJ repair is known to be an error-prone pathway, genomic instability might be increased in PRMT5-overexpressing cells, leading to a pro-growth tumor phenotype." (PMID 32759981, 2020). "Notably, MEN1 mutations, which are frequently seen in inherited tumor syndromes, relieve repression by PRMT5, enabling oncogenic signaling and tumor growth." (PMID 32743345, 2020). "Indeed, recent studies have demonstrated a redundancy between PRMT1 and PRMT5 pathways and synergistic anti-tumor effects of combined inhibition of both PRMTs23–25." (PMID 32415090, 2020). "Tumor intrinsic alteration of splicing through the frequently seen mutation in RNA splicing factors (SRSF2, SF3B1 and U2AF1) in AML cells confers vulnerability to either PRMT1 inhibition (MS023,), PRMT5 inhibition (GSK3203591,), or both." (PMID 32743345, 2020). "However, given the complexity of the tumor microenvironment, further studies are needed to determine how systemic PRMT5 inhibition, either singly or in combination with ICT, would affect anti-tumor immunity." (PMID 32743345, 2020). "In addition, PRMT5 affects BUC tumor progression by distorting the Rb and p27 proteins involved in the cell cycle and facilitating the PI3K/Akt/mTOR signaling pathway." (PMID 32392182, 2020). "Tumor growth inhibition induced by knockdown of PRMT5 was restored by ectopic expression of Wnt4." (PMID 33060569, 2020). "Indeed, PRMT5 depletion/inhibition sensitizes tumor cells to drugs inducing the DDR, exemplified by cytarabine (MLL-rearranged leukemia,), PARP inhibitors (AML,) and camptothecin, a topoisomerase inhibitor." (PMID 32743345, 2020). "PRMT5 contributes to anti-tumor immunity by altering two distinct tumor intrinsic pathways." (PMID 32743345, 2020).
tumor (continued). "Moreover, accumulating evidence suggests that PRMT5 exerts its pro-tumor functions through methylation of several pleotropic transcription factors (TFs)." (PMID 32456215, 2020). "It is indicated that PRMT5 also significantly increased tumour growth." (PMID 31851779, 2020). "Furthermore, similarly to NAA40, PRMT5 expression levels are also increased in all tumor stages in CRC patients." (PMID 30858358, 2019). "We noted DS-437 does not affect the tumor associated macrophage's phenotype, suggesting that PRMT5 inhibition during anti-erbB2 mAb therapy would not be dependent on the macrophage activity." (PMID 30800128, 2019). "We next sought to determine whether inhibition of PRMT5 could improve anti-p185erbB2/neu targeted therapy in the resistant tumor model." (PMID 30800128, 2019). "In addition, certain tumor suppressors, such as the metastasis inhibition factor Nm23, can be epigenetically silenced by PRMT5." (PMID 30922330, 2019). "Our experiments indicate that limiting PRMT5 function may promote tumor immunity by inhibiting Treg function and limiting Treg migration into tumors." (PMID 30800128, 2019). "LINC01138 acts as an oncogenic driver that promotes cell proliferation, tumorigenicity, tumour invasion and metastasis by physically interacting with arginine methyltransferase 5 (PRMT5) and enhancing its protein stability by blocking ubiquitin/proteasome-dependent degradation in HCC." (PMID 29679004, 2018). "Notably, LCE1 genes are downstream targets of p5312 and have tumor suppressor functions through modulating the activity of protein arginine methyltransferase 5 (PRMT5)." (PMID 29559659, 2018). "In addition, xenograft tumor sections were stained for Ki67 to observe tumor proliferation status, which indicated that tumors derived from cells with stably silenced PRMT5 showed significantly reduced proliferation." (PMID 29441724, 2018). "Importantly, to mimic a patient presenting with disease, we depleted PRMT5 in an established tumour xenograft which led to a substantial 12-fold decrease in stem cell numbers as assessed by limiting dilution." (PMID 29876520, 2018). "In addition, PRMT5 overexpression significantly increased the invasion abilities of these cells, confirming that PRMT5 is a tumour-promoting gene in HCC." (PMID 29679004, 2018). "Correlation analysis demonstrated that PRMT5 expression was positively correlated with tumor size." (PMID 29441724, 2018). "Our findings provide compelling evidence that drug targeting PRMT5 could have significant clinical benefit in solid cancers enabling the complete eradication of the tumour-initiating population to improve long-term patient survival." (PMID 29876520, 2018). "Furthermore, we found that treatment of BCSCs isolated from resected primary tumours with a pre-clinical PRMT5 inhibitor significantly reduced BCSC numbers." (PMID 29876520, 2018). "Importantly, PR5-LL-CM01 showed higher anti-tumor efficacy than the commercial PRMT5 inhibitor, EPZ015666, in both PDAC and CRC." (PMID 28591716, 2017). "Recent studies indicated that inhibition of PRMT5 suppressed proliferation in tumour cell lines." (PMID 27860244, 2017). "Here, we define for the first time a significant role of PRMT5 as a tumor promoter in PDAC and CRC." (PMID 28591716, 2017). "Importantly, and in agreement with our limiting dilution analysis using bulk cell population, depletion of PRMT5 affected the tumor-initiating capacity of only ESA+CD24lowCD44+ BCSCs, not the differentiated population." (PMID 29262329, 2017).
tumor (continued). "Recent studies have shown that PRMT5 regulates tumor growth by modulating cyclin D1 expression." (PMID 28107179, 2017). "Protein arginine methyltransferase 5 (PRMT5) is an enzyme which can transfer methyl groups to the arginine residues of histones and some nonhistone proteins, and its methyltransferase activity is necessary for tumor cell proliferation." (PMID 27708221, 2016). "The R110 of PDCD4 and the catalytic activity of PRMT5 are necessary for tumor growth." (PMID 27556302, 2016). "Furthermore, injection of HepG2 cells transfected with CDK4 WT/PRMT5 also resulted in a larger tumor width and tumor weight than those with CDK4 R24A/PRMT5." (PMID 27708221, 2016). "Our results suggested that the weak binding of CDK4 R24A with PRMT5 inhibited HCC tumor growth." (PMID 27708221, 2016). "In contrast, injections of formulated si-PRMT5 specifically blocked tumor growth in nude mice." (PMID 26078354, 2015). "As Cyclin D1 is a downstream target of Wnt/β-catenin pathway and plays a key role as a regulator of cell proliferation, these data suggest that PRMT5 might mediate HCC tumor proliferation and development by regulating Cyclin D1 through Wnt/β-catenin pathway." (PMID 26541651, 2015). "Moreover, coronin 2A interacted with PRMT5 (protein arginine N-methyltransferase 5), which modulates the sensitivity of tumour cells to TRAIL-induced cell death." (PMID 26373535, 2015). "Chromatin remodeling complexes and associated co-repressors such as histone deacetylases (HDAC), DNA methyltransferases (DNMT), and protein arginine methyltransferase 5 (PRMT5) participate in silencing tumor suppressor gene expression and contribute to cellular transformation." (PMID 26729154, 2015). "However, histologic examination of tumor xenografts revealed a heterogeneous pattern of nuclear and cytoplasmic PRMT5 expression." (PMID 24098663, 2013). "PRMT5 likely plays a unique role across individual tumor types." (PMID 24098663, 2013). "In the future our studies will focus on examining the relationship between PRMT5 expression and tumor stage, or between primary tumors and biopsies from locally positive sentinel lymph nodes, in order to identify if PRMT5 could be a prognostic marker." (PMID 24098663, 2013). "However, histologic examination of tumor xenografts from athymic mice revealed heterogeneous nuclear and cytoplasmic PRMT5 expression." (PMID 24098663, 2013). "Moreover, combined PRMT5 and PD-1 inhibition led to enhanced in vivo anti-tumor activity." (PMID 41439984, 2025). "Consequently, our study aimed to address two notable gaps in the literature: (i) the mechanism of regulation of PRMT5 expression under hypoxia and (ii) the impact of PRMT5-mediated alternative splicing via histone methylation on tumor progression under hypoxia." (PMID 41150697, 2025). "Therefore, we conducted further investigations to assess whether PRMT5 influenced the effect of CD8+ T cells on in vivo tumor growth." (PMID 41463372, 2025). "Notably, those tumors with low PRMT5 levels had uniformly and significantly upregulated PRMT5 expression in a post-chemotherapy recurrent state, implying that PRMT5 may be a key determinant of tumor recurrence and chemoresistance." (PMID 40091834, 2025). "In addition, knockdown of PRMT5 results in an increased expression of the epithelial marker E-cadherin (at both mRNA and protein levels) and decreased expression of the mesenchymal markers Vimentin, Collagen I, and β-catenin, indicating that PRMT5 is involved in tumor metastasis." (PMID 38612768, 2024). "Therefore, we examined whether the inhibition of PRMT5 activity is a drug target in NDRG2low tumours." (PMID 38474089, 2024). "PRMT5 inhibitors in both isoforms may help in tumor regression." (PMID 38827324, 2024).